VCAN (versican)
Diseases named in the same sentence as VCAN in open-access papers (continued):
Sharing a sentence is not in itself a finding about the gene and the disease.
tumor (continued). "VCAN is involved in tumor proliferation, migration and angiogenesis, which plays an important role in histomorphology." (PMID 35832544, 2022). "At the same time, a recent study shows that RhoGDI2 suppresses lung metastasis in mice by reducing tumor versican expression and macrophage infiltration." (PMID 35111402, 2022). "Single cell RNA sequencing and bulk RNA sequencing data was utilized to explore the role of VCAN in tumor microenvironment." (PMID 36203562, 2022). "In this model, tumor-derived versican was responsible for macrophage recruitment to the metastatic niche." (PMID 36224342, 2022). "High stromal expression of Versican correlates with poor tumor differentiation, disease recurrence, advanced tumor stage, and lymph node metastases." (PMID 34503301, 2021). "VCAN was a member of the large aggregating chondroitin sulfate proteoglycan (CSPG) family; it is an important ECM component, which has been implicated in tumor progression." (PMID 33604385, 2021). "The immunohistochemical staining results indicated that a higher expression level of VCAN was confirmed in the tumor tissues." (PMID 34820403, 2021). "Versican (a matrix proteoglycan) is secreted by tumor cells and stimulates metastasis through TLR2 signaling in myeloid cells." (PMID 34032639, 2021). "From the data acquired by multiple groups studying versican in various tumours, it is evident that the isoforms V0 and V1 are the most dominant and have the greatest impact on tumourigenesis." (PMID 34527586, 2021). "As COX analysis performed, Stage IV and VCAN both had significant p value, which indicated that both Stage IV and VCAN expression were significant tumor promoter in GC." (PMID 33631054, 2021). "High expression of VCAN was detected in 48 of 88 (54.5%) cases of patients with a single tumor and in 245 of 329 (62.5%) cases of patients with multiple tumors, which showed a significant difference (χ2 = 13.19, P < 0.001)." (PMID 33604385, 2021). "Tumor cell-derived versican can also induce the upregulation of PD-L1 on monocytes and macrophages, an important molecular driver of T cell exhaustion." (PMID 33708224, 2021). "Of possibly greater concern was that VCAN has been proven to promote cell proliferation, inhibit apoptosis, and promote metastasis in the tumor." (PMID 33604385, 2021). "The expression of LUM and VCAN negatively correlated with tumor purity, whereas the expression of EFNA4 positively correlation with tumor purity." (PMID 34093807, 2021). "Compared with normal kidney tissues, antibody stainings for ANKZF1, CD44, IDUA, KIF20A, PLOD2, and VCAN were high in ccRCC tumor tissues, whereas they were low for CHST6, HS6ST2, NDST3 and FBP1." (PMID 33836688, 2021). "In the TME, myeloid cells produce versican and promote tumor metastasis and increased versican in tumors correlated with reduced CD8+ T cells infiltration." (PMID 33708224, 2021). "TLR2 activation by versican also reduces dendritic cell anti-tumour response through IL-10 and IL-6 signalling, leading to the mitigation of conventional dendritic cell responses required for further downstream T cell activation." (PMID 34527586, 2021). "A growing body of evidence suggests that versican and its proteolytic products are active modulators of the tumor microenvironment promoting pro or antitumor effects by different mechanisms." (PMID 33804223, 2021). "The downregulation of IRF9 and VCAN expression was conserved until tumor excision, STAT1, and CDKN1A expression showed decreased tendency and STAT2, and PCNA expression were significantly reduced in the IRF9-knockdown group." (PMID 33430083, 2021). "In this type of tumor, macrophages produce versican V1 to induce a tolerogenic response mediated by the production of the type II cytokines interleukin-4 (IL-4), IL-5 and IL-10 due to the interaction of the hyalectan with antigen-presenting cells." (PMID 33804223, 2021).
tumor (continued). "Spearman's correlations between the expression of VCAN and tumor-infiltrating lymphocytes (Y-axis) across human cancers (X-axis) were also demonstrated." (PMID 34820403, 2021). "The depletion of VCAN in QRsP11 murine fibrosarcoma cells was demonstrated to promote tumor growth and angiogenesis in the mouse model." (PMID 34852849, 2021). "Versican does have contrary roles within the TME as it is involved in both tumour progression and inhibition." (PMID 34527586, 2021). "In cancer-associated fibroblasts (CAF), proteoglycan synthesis shifted from DCN to versican, biglycan, and type I collagen, resulting in tumor-supportive ECM formation, which allowed the spreading of the tumor." (PMID 34884232, 2021). "VCAN participates in cancer-related intercellular substance formation to promote tumor cell proliferation and invasion in multiple types of cancers." (PMID 34987579, 2021). "Tumor cell-derived versican in turn promotes accumulation and secretion of proinflammatory TNFα and IL-6." (PMID 32265939, 2020). "Cervical and endometrial cancers are characterized by increases in versican originating from both tumor and stromal cells." (PMID 32265939, 2020). "Accumulation of versican in tumors is positively correlated with the number of microvessels within tumor stroma." (PMID 32265939, 2020). "According to these observations, we found VCAN diffusely expressed in the tumor cells of all the datasets considered." (PMID 33155039, 2020). "Perturbing the accumulation of versican in tumors can inhibit inflammation and tumor progression in some cancers." (PMID 32265939, 2020). "Higher expression of VCAN has been reported in angiogenesis, tumor growth, cancer relapse, and inflammatory lung disorders." (PMID 32575462, 2020). "Blocking versican synthesis with siRNA to versican reduced the thickness of the cell coats and inhibited their proliferation and migration in vitro and tumor formation in vivo." (PMID 32265939, 2020). "Hyaluronan and versican (VCAN), via binding the same receptors, were found to promote tumor cell proliferation and metastatic ability." (PMID 33199679, 2020). "Hartley and colleagues showed that versican produced by mouse tumor cells stimulated monocytes to produce TNFα in a TLR2-dependent manner which in turn upregulated the expression of PD-L1 by mouse monocyte/macrophages." (PMID 32265939, 2020). "Edwards, in 2012, discussed that in PC, decorin, which also interacts with TGF-b, and betaglycan inhibit tumor growth and metastasis, while versican and perlecan respectively promote cell motility and invasion, and tumor cell growth and angiogenesis." (PMID 32847060, 2020). "Namely, the CAF-derived proteoglycans versican and serglycin promote tumor invasion and metastasis in breast, ovarian, and prostate cancer, as well as NSCLC cells EMT, migration, invasion and liver colonization, respectively." (PMID 31157165, 2019). "Gene ontology analysis of these DEGs showed that in advanced stage tumours, pathways such as cell adhesion (VCAN), ECM receptor interaction (COL1A2, COL3A1, ITGA11, and TNN) and pathways in cancer (JUN, and MYC) getting deregulated." (PMID 31292488, 2019). "In this context, the intrinsic TLR2 ligand versican promotes tumor progression and the tumor-derived TLR2 ligand hyaluronan induces formation of immunosuppressive macrophages." (PMID 31019508, 2019). "On day 14, collagen deposition was observed most frequently in peritumoral and necrotic areas and less frequently in the versican-expressing tumor stroma." (PMID 31334111, 2019). "Positive versican expression in tumor epithelial and stromal cells was found in 39.5% and 22.4% of tumors, respectively." (PMID 31531098, 2019). "In a similar way to that occurring in cardiogenesis or tumor processes, versican degradation by proteolysis is a critical event in web regression." (PMID 31508361, 2019). "Versican, a member of the aggregating chondroitin sulfate proteoglycans family, is accumulated predominantly in the tumor stroma." (PMID 31531098, 2019).
tumor (continued). "Different studies have described that versican stimulates cell growth and inhibits cell adhesion, both processes related to tumor progression." (PMID 31534630, 2019). "Versican is a large hyaluronan-binding proteoglycan observed in increased quantities in tumor cells." (PMID 31531098, 2019). "Recently one study showed that versican directly facilitates tumour growth by promoting angiogenesis, and it was impaired in versican haploinsufficient mice resulting in reduced tumour growth." (PMID 31263118, 2019). "We next investigated the contribution of inflammatory mediators in the 4T1 tumor microenvironment and its relationship with versican expression." (PMID 31334111, 2019). "This interplay is suggested to enhance the “T-cell inflammation,” response and downregulate the “tolerogenic consequences of intact versican accumulation” contributing to tumor restraint." (PMID 31068944, 2019). "Depending on the cancer type, versican is expressed by either the cancer cells themselves and/ or by stromal cells surrounding the tumor." (PMID 31531098, 2019). "The metastatic progression of the 4T1 tumor was accompanied by the up-regulation of versican expression in neoplastic cells of the primary tumor, which was correlated with the number of pulmonary metastatic nodules." (PMID 31334111, 2019). "We measured gene expression (mRNA levels) of adiponectin, leptin and versican, in adipose tissue explants from normal (hRAN) and tumor (hRAT) kidney." (PMID 31534630, 2019). "For instance, ADAMTS-1 can promote tumor growth and progression in both breast and ovarian cancers and can induce pathological angiogenesis through versican degradation." (PMID 31508361, 2019). "Elevated level of VCAN correlated with higher tumor grade and invasiveness in carcinomas with MD and MAMCs." (PMID 29747682, 2018). "The observation that LY treatment is associated with reduced expression of VCAN and COL11A1 in tumor stroma provides evidence of a potential TGF-β-dependent mechanism of growth inhibition." (PMID 30087253, 2018). "The utilization of microarray expression profiling on a group of 84 matched clear cell renal carcinoma and normal renal tissues determined a higher expression of the hyalectan, versican in tumor tissues." (PMID 29559954, 2018). "Here, we investigated the contribution of stromal production of versican and of versican cleavage to tumor angiogenesis." (PMID 29222454, 2017). "For approximately half of all tumor samples (50 and 53 for lumican and versican, respectively) such mRNA data were available." (PMID 28481899, 2017). "Versican is a secreted proteoglycan protein with diverse functions that can promote tumor progression and its high expression is reported to be associated with unfavorable prognosis." (PMID 28035060, 2017). "Several members of the family of A disintegrin-like and metalloproteinase with thrombospondin type 1 motifs (ADAMTS) are involved in versican proteolysis and tumor progression." (PMID 29222454, 2017). "Because versican haploinsufficiency impaired proper tumor vessel invasion, it will be important to discriminate between the roles of intact and cleaved versican." (PMID 29222454, 2017). "Our studies suggest that where tumor-derived versican is present in addition to stromal versican there will be higher overall versican levels." (PMID 29222454, 2017). "Since recent studies have demonstrated that macrophages are essential for tumor angiogenesis, we examined the localization of macrophages (F4/80+ cells) in relation to versican." (PMID 29222454, 2017). "Versican can also activate resident fibroblasts and endothelial cells in tumor stroma through toll-like receptors (TLR) 2 and TLR6, resulting in enhanced neovascularization." (PMID 28035060, 2017). "The results indicate that versican is tumor-promoting protein, and inhibition of versican expression suppresses the migration and invasion ability of SCC15 cells." (PMID 28035060, 2017).
tumor (continued). "By immunoblotting, we first confirmed versican GAGβ reduction in Vcanhdf/+ mouse tumor as compared with that of wild-type." (PMID 29222454, 2017). "In contrast to Western blots of the cell lines, the tumor Western blots showed abundant versican, although mostly in a variety of cleaved forms." (PMID 29222454, 2017). "Our findings suggest that, in addition to the tumor-derived versican, the stroma-derived versican is extremely relevant in specific cancer models." (PMID 29222454, 2017). "We measured genetic expression (mRNA levels) of versican, adiponectin and leptin in adipose tissue far away (hRATfT) and near (hRATnT) tumor cells." (PMID 29212223, 2017). "We performed an immunohistochemistry assay on adipose tissue far away (hRATfT) and near (hRATnT) tumor cells, in order to measure versican, adiponectin and leptin levels and localization in both tissue samples." (PMID 29212223, 2017). "Versican localized preferentially to the vicinity of tumor vasculature and macrophages in the tumor." (PMID 29222454, 2017). "Taken together, our findings suggest that versican is an intriguing target to consider in combating tumor growth and angiogenesis." (PMID 29222454, 2017). "Versican has been found to promote tumor development and metastasis through stimulation of cell proliferation and by increasing cell motility in several cancer types." (PMID 28481899, 2017). "In contrast to the present analysis, the authors of that study concluded that stromal versican was inhibitory to angiogenesis and tumor growth." (PMID 29222454, 2017). "Next, lumican and versican protein expression levels were compared to their mRNA expression levels in corresponding tumor samples." (PMID 28481899, 2017). "Microarray analysis identified that Versican, a chondroitin sulfate proteoglycan that plays crucial roles in tumor progression and invasion, was also upregulated in Sharpin-expressing stable cells." (PMID 27941932, 2016). "In this way, VCAN plays a role in determining the consistency and appearance of tumour spots on the peritoneal surface, thereby possibly contributing to the extent to which these spots can be detected and subsequently resected." (PMID 26873137, 2016). "Versican expression promotes tumor growth by destabilizing focal cell contacts, thus impeding cell adhesion and facilitating cell migration." (PMID 27490467, 2016). "Versican, an ECM component, is a member of the large aggregating chondroitin sulfate proteoglycan (CSPG) family and has been implicated in tumor progression." (PMID 27490467, 2016). "The sulphate proteoglycan VCAN is thought to promote tumour development by mediating several processes such as proliferation, drug resistance, cell adhesion, invasion and angiogenesis." (PMID 26873137, 2016). "The influence of molecules such as VCAN in tumour response to chemotherapy stresses the importance of systematically analysing interactions between cancer cells and their environment in order to identify mechanisms contributing to drug sensitivity." (PMID 26873137, 2016). "The search for new biomarkers and more effective therapeutic targets in cancer treatment warrants the interest in versican and its role in tumor progression." (PMID 27490467, 2016). "VCAN is a sulphate proteoglycan overexpressed in a variety of human malignant tumours, including CRC." (PMID 26873137, 2016). "Sharpin overexpression led to increased expression of Versican, an aggregating chondroitin sulfate proteoglycan that plays biological roles in tumor progression and invasion, leading to HCC cell invasion." (PMID 27941932, 2016). "Additional significant information would give a study in ADAMTSs expression in CRC, since a potential degradation of versican would result in active versican fragments with established roles in tumor progression." (PMID 25786261, 2015). "High Versican mRNA and protein expression correlated with greater tumor invasion depth (P=0.030, P=0.027)." (PMID 26619403, 2015).
tumor (continued). "Previous work in the lab has demonstrated the ability of hCG to enhance the secretion of versican from tumor cells, resulting in the release of these inflammatory cytokines in a TLR-2 dependent manner (data not shown)." (PMID 26608647, 2015). "Tumor-derived versican (a proteoglycan which sequesters chemokines and acts as a chemo-attractant for inflammatory cells in the tumor milieu) can stimulate resident macrophages to secrete IL-6 and TNF-α in a TLR-2 dependent manner." (PMID 26608647, 2015). "Multivariate analysis revealed that in addition to the tumor stage (P=0.001), Versican expression was an independent prognostic indicator for DSS in GC patients (P=0.002)." (PMID 26619403, 2015). "TGF-β1 and versican are involved in the molecular mechanism of tumor sphere formation TGF-β1 is a triggering molecule and stimulates versican, and our study also showed that versican is involved in resistance to ES." (PMID 26705466, 2015). "The group with higher Versican mRNA and protein expression exhibited deeper tumor invasion than the lower Versican expression group." (PMID 26619403, 2015). "Versican was majorly expressed in the stroma surrounding tumor epithelium and minorly some areas of tumor epithelium." (PMID 26619403, 2015). "The biological function of versican has previously been shown to generate a hospitable microenvironment for tumor invasion and metastasis." (PMID 25859560, 2015). "The effect of versican on the tumor environment appeared to provide the opportunity of tumor cells to get easily metastasis and invasion." (PMID 25859560, 2015). "Versican, a member of the aggregating chondroitin sulfate PGs family, is accumulated predominantly in the tumor stroma, providing hygroscopic properties to create a loose and hydrated matrix that is necessary to support key events in development and disease." (PMID 26619403, 2015). "We detected marked growth inhibition of ACC tumor cells in vitro and also reduced nude mouse xenograft tumor growth in vivo with both VCAN shRNAs." (PMID 25587024, 2014). "Three genes, including NETO2, GBP2, and VCAN, showed consistent high expression across these 90 tumor samples." (PMID 24783204, 2014). "We observed that forced MYB-NFIB expression in human salivary gland cells alters cell morphology and cell adhesion in vitro and depletion of VCAN blocked tumor cell growth of a short-term ACC tumor culture." (PMID 25587024, 2014). "For instance, activation of TLR2 and TLR6 in macrophages enhances metastasis of tumor cells, wherein receptor activation is mediated by tumor cell-derived versican, an extracellular matrix proteoglycan that is up-regulated in many tumor cells." (PMID 25149452, 2014). "Our recent study demonstrated the preferential engagement of immunosuppressive M2 macrophages in a HA- and versican-rich tumor microenvironment." (PMID 25125485, 2014). "Versican (VCAN) is a secreted proteoglycan protein with multiple functions that can promote tumor metastasis." (PMID 24999371, 2014). "Decorin, mimecan, hemoglobin subunit alpha, hemoglobin subunit beta, and keratin type I cytoskeletal 19 were upregulated in normal tissue, whereas periostin and versican core protein were upregulated in phyllodes tumor tissue." (PMID 25400079, 2014). "In most tumor types the tumor stroma is abundant in matrix PGs, particularly versican, lumican, and fibromodulin, and this suggests an important role of stromal PGs in controlling tumor progression." (PMID 24392351, 2013). "Here we report the versican V1 derived from tumor cells enhances hCAP18/LL-37 expression in macrophages through the activation of TLR2 and subsequent vitamin D-dependent mechanisms." (PMID 23424670, 2013). "Several reports have recently revealed that the ECM proteins fibronectin, tenascin-C, periostin and versican play essential roles as components of the metastatic niche for tumor-initiating cells that invade the lungs." (PMID 23951338, 2013).